LINC00526 (long independently transcribed non-coding RNA 526)
Synonyms: MGC17515; HsT959; TP53LC13; formerly C18orf18
Gene: Long non-coding RNA gene on chromosome 18 (5,232,876 to 5,239,390, reverse strand). Ensembl gene ENSG00000264575.
Diseases named in the same sentence as LINC00526 in open-access papers:
LINC00526 is named in the same sentence as 13 diseases in open-access papers, as found by Europe PMC text mining. Sharing a sentence is not in itself a finding about the gene and the disease. The quoted sentences say what the papers report.
glioma (3 papers, 2019 to 2021). A benign or malignant brain and spinal cord tumor that arises from glial cells (astrocytes, oligodendrocytes, ependymal cells). "Bioinformatic analysis and rescue experiments tool showed that LINC00526 regulates microRNA-5581-3p (miR-5581-3p)/brain-expressed X-linked 1 (BEX1) axis to suppress glioma progression." (PMID 33613672, 2021). "Through searching TCGA data, we found that the expression of AXL was significantly inversely associated with that of LINC00526 in glioma tissues." (PMID 31240814, 2019). "The TCGA data revealed that low expression of LINC00526 is associated with poor survival of glioma patients." (PMID 31240814, 2019). "Low expression of LINC00526 was associated with the aggravation and poor prognosis of glioma." (PMID 31240814, 2019). "Another work showed low LINC00526 expression was an indicator for poorer overall survival of glioma patients." (PMID 33613672, 2021). "LINC00526 was found to be decreased in glioma tissues and cell lines compared with their normal counterparts." (PMID 33613672, 2021). "Silencing the expression of LINC00526 promotes, while forcing its expression, inhibits glioma cell growth and invasion." (PMID 33613672, 2021). "LINC00526 expression in glioma tissues and cells and their normal counterparts was measured with quantitative real-time polymerase chain reaction method." (PMID 33613672, 2021). "Firstly, we found the LINC00526 expression level was significantly decreased in glioma tissues compared with the matched normal tissues." (PMID 33613672, 2021). "In this study, we identified a novel lncRNA LINC00526, which is significantly low expressed in glioma." (PMID 31240814, 2019). "Functional assays revealed that ectopic expression of LINC00526 inhibits glioma cell proliferation, migration, and invasion." (PMID 31240814, 2019). "Our data also suggested LINC00526 as a potential prognostic biomarker and therapeutic candidate for glioma." (PMID 31240814, 2019). "Gain‐of‐function and loss‐of‐function assays demonstrated that ectopic expression of LINC00526 inhibited glioma cell proliferation, migration and invasion." (PMID 31240814, 2019). "Multi‐centre analyses of the correlation between LINC00526 expression and prognosis of glioma patients would further detect the potential of LINC00526 as a prognostic biomarker, which needs further investigation." (PMID 31240814, 2019). "To determine the influences of LINC00526 on glioma cells, we stably ectopically expressed LINC00526 in U87 and U251 cells." (PMID 31240814, 2019). "To investigate the potential mechanisms mediating the tumour suppressive roles of LINC00526 in glioma, we analysed the expression correlations between LINC00526 and mRNAs in glioma tissues using TCGA data." (PMID 31240814, 2019). "LINC00526 inhibited glioma cell proliferation, migration and invasion via the LINC00526/EZH2/AXL/NF‐κB/LINC00526 feedback loop." (PMID 31240814, 2019). "In contrast to LINC00526, higher expression of AXL was associated with shorter survival time in glioma patients." (PMID 31240814, 2019). "In this study, we identified a novel lncRNA LINC00526, which is down‐regulated and functions as a tumour suppressor in glioma." (PMID 31240814, 2019). "To further confirm the tumour suppressive roles of LINC00526 in glioma, we stably silenced the expression of LINC00526 in U87 and U251 cells using two independent LINC00526 specific shRNAs." (PMID 31240814, 2019). "In this study, we further explored the molecular mechanisms mediating the down‐regulation and tumour suppressive roles of LINC00526 in glioma." (PMID 31240814, 2019). "Analysis of the TCGA data revealed that the expression of LINC00526 is inversely correlated with that of AXL in glioma tissues." (PMID 31240814, 2019). "Furthermore, we found LINC00526 was expressed at a lower level in glioma cells than in normal cells." (PMID 33613672, 2021).
glioma (continued). "Hence, with the knowledge that LINC00526 expression was reduced in glioma, we then overexpress it in the glioma cells." (PMID 33613672, 2021). "This work was aimed to investigate the biological functions of LINC00526 in glioma." (PMID 33613672, 2021). "Functions of LINC00526 in glioma were investigated with in vitro experiments." (PMID 33613672, 2021). "In summary, we revealed LINC00526 expression was reduced in glioma." (PMID 33613672, 2021). "Functional assays indicated LINC00526 overexpression could suppress glioma cell proliferation and invasion." (PMID 33613672, 2021). "We first measured LINC00526 expression level in 41 glioma tissues and 11 normal tissues." (PMID 31240814, 2019). "We first confirmed the significant down‐regulation of LINC00526 in human glioma tissues." (PMID 31240814, 2019). "Low expression of LINC00526 is correlated with aggravation and poor survival in glioma." (PMID 31240814, 2019). "LINC00526 was obviously lowly expressed in glioma tissues compared with normal tissues." (PMID 31240814, 2019). "In summary, this study identified a novel lncRNA LINC00526, which is lowly expressed in glioma." (PMID 31240814, 2019). "Thus, this study identified LINC00526 as a potential prognostic biomarker and a candidate for therapy in glioma." (PMID 31240814, 2019). "LINC00526 silencing promotes glioma cell proliferation, migration and invasion." (PMID 31240814, 2019). "Reciprocally, LINC00526 silencing promoted glioma cell proliferation, migration and invasion." (PMID 31240814, 2019). "LINC00526 expression levels were inversely correlated with aggravation of glioma." (PMID 31240814, 2019). "Next, we investigated whether the tumour suppressive roles of LINC00526 in glioma are dependent on AXL." (PMID 31240814, 2019). "Besides that, LINC00526 was reported to interact with EZH2 to repress glioma progression." (PMID 33613672, 2021). "However, the detailed mechanisms of LINC00526 in glioma remain to be further investigated." (PMID 33613672, 2021). "Therefore, our data identified LINC00526 as a potential prognostic biomarker for glioma and suggested that ectopic expression of LINC00526 may be a potential therapeutic strategy for glioma." (PMID 31240814, 2019). "Moreover, LINC00526 was further decreased in aggravated glioma tissues." (PMID 31240814, 2019). "Therefore, LINC00526/EZH2/AXL/PI3K/Akt/NF‐κB form a feedback loop in glioma." (PMID 31240814, 2019). "LINC00526 is a long intergenic non-protein-coding RNA, and one study has demonstrated that it suppresses glioma progression." (PMID 31516386, 2019). "Furthermore, LINC00526 expression level in normal glia cell line NHA and glioma cell lines LN18, U87, U251 and U138 was measured." (PMID 31240814, 2019). "Collectively, our data identified LINC00526 as a tumour suppressor in glioma via forming a double negative feedback loop with AXL." (PMID 31240814, 2019). "Therefore, LINC00526 and AXL form a double negative feedback loop, which further promotes the down‐regulation of LINC00526 and the up‐regulation of AXL in glioma tissues." (PMID 31240814, 2019).
bladder cancer (1 paper, 2025). "The hypermethylation of C18orf18, also known as LINC00526, has been associated with poor prognosis and survival in bladder cancer." (PMID 39858027, 2025).
thymoma (1 paper, 2024). A neoplasm arising from the epithelial cells of the thymus. "Upregulation of LINC00668 gene occurs in COAD, READ, STAD, and LUSC, of LINC00526 and LINC00667 genes occurs in thymoma (THYM), and of LINC01443 gene occurs in skin cutaneous melanoma (SKCM)." (PMID 38540157, 2024). "LINC00526 and LINC00667 genes are co-expressed with genes participating in the processing of capped intron-containing pre-mRNA, RNA processing, and transcriptional and post-transcriptional regulation of gene expression in thymoma." (PMID 38540157, 2024).
cancer (3 papers, 2019 to 2025). A tumor composed of atypical neoplastic, often pleomorphic cells that invade other tissues. "Thus, LINC00526 and LINC00667 are represented in the majority of pathways in different cancer types." (PMID 38540157, 2024).
tumor (3 papers, 2019 to 2024). "At the same time, there are associations of LINC00526 gene promoter methylation with patients’ survival rates in UCEC (46 normal and 432 tumor cases) and an inverse relationship between an increase in promoter methylation of LINC00526 gene and a decrease in its gene expression levels." (PMID 38540157, 2024). "It was found LINC00526 overexpression could reduce tumor size and tumor weight, which is in consistent with the in vitro analyses results." (PMID 33613672, 2021). "In addition, functional rescue assays revealed that the tumour suppressive roles of LINC00526 are dependent on the negative regulation of AXL." (PMID 31240814, 2019). "In vivo experiments showed forced LINC00526 expression could suppress tumor growth." (PMID 33613672, 2021).
LINC00526 also shares sentences with these, for which no sentence is quoted: cervical cancer (1 paper); cutaneous melanoma (1); hepatocellular carcinoma (1); leiomyosarcoma (1); lung carcinoma (1); prostate carcinoma (1); renal carcinoma (1); testicular germ cell tumor (1).